IL7 (interleukin 7)
Diseases named in the same sentence as IL7 in open-access papers (continued):
Sharing a sentence is not in itself a finding about the gene and the disease.
cancer (continued). "We investigated the therapeutic effects of next-generation chimeric antigen receptor (CAR) T cells producing IL7 and chemokine (C–C motif) ligand 19 (CCL19; referred to as 7 × 19 CAR-T) in these intractable cancers." (PMID 39240078, 2024). "Candidate biomarkers such as IL-7, TWEAK, 4E-BP, CXCL5, and CD5 are all actively involved in cancer initiation and progression in previous reports, and the KEGG analysis also indicated cancer pathway enrichment." (PMID 38455059, 2024). "With the emergence of cytokine therapy for cancer, the four cytokines of the common cytokine receptor γ chain (γc, CD132) family, containing interleukin-2 (IL-2), IL-7, IL-15, and IL-21 are dictated to regulate the T cell stemness formation and maintenance." (PMID 38049832, 2023). "As interleukin‐7 (IL‐7) is necessary for proliferation of lymphocytes and to increase total lymphocyte count (TLC), IL‐7 therapy has been attempted in various cancers." (PMID 36583472, 2023). "Noteworthy among these are IFNγ, which plays a role in both innate and adaptive antitumor response, and IL7, which presents antitumor effects by increasing CD8+ T-cell infiltration, and is also the subject of cancer trials." (PMID 36860652, 2023). "Therefore, IL-7 might mitigate the side effects of using IL-2 in cancer immunotherapy." (PMID 36142322, 2022). "IL-7 enhances the cytotoxicity of NK, NKT, lymphokine-activated killer (LAK) cells, monocytes, and cancer-specific cytotoxic T lymphocytes (CTLs)." (PMID 36142322, 2022). "MANOVA on these genes reveals that this combined set of 7 genes (MYC, CD40LG, CCL4, IL7, TCF4, CCR7 and FASLG) is together statistically significantly reliant on both time post-exposure (p = 0.042) and cancer type (p < 0.001)." (PMID 33941218, 2021). "The bone marrow serves as a reservoir for memory CD4+ T cells and memory CD8+ T cells, where they seem to be attracted by bone-derived cytokines, such as IL-7, and, interestingly, CXCL12, similar to cancer cells." (PMID 32326073, 2020). "The use of interleukin-7 (IL-7) as an immunorestorative therapeutic has proven effective in HIV infection, cancer and bone marrow transplantation." (PMID 29261677, 2017). "An inverse relationship between circulating IL-7 levels and CD4 T cell counts was consistently found in various clinical settings including cancer and HIV infection, suggesting that IL-7 plays a unique role in maintaining lymphocyte homeostasis." (PMID 23251223, 2012). "Several clinical trials using IL-7 are currently underway in cancer, HIV, HBV and HCV infections to remediate disease-associated immune deficits and our results in mice suggest that increasing IL-7 levels may also affect fat mass development and insulin sensitivity in the IL-7-treated patients." (PMID 22768283, 2012). "We showed significantly higher IL-7 levels in supernatants derived from PBMC cultures and co-coltures of monocytes and T or B cells of cancer patients compared to healthy controls." (PMID 17205128, 2006). "This case series evaluated exploratory metabolic imaging correlates using [18F]-FDG PET/CT in mCRPC patients enrolled in a Cancer Immunotherapy Trials Network (CITN) trial of sipuleucel-T (sip-T) with or without recombinant interleukin-7 (IL-7)." (PMID 42278652, 2026). "In cancer treatment studies, IL-7 boosted CD4+ and CD8+ T cell subpopulations but not Treg expansion and increased TCR repertoire diversity." (PMID 40370435, 2025). "Despite promising advancements, no comprehensive review exists on IL-7 expression in virus-based immunotherapy for cancer." (PMID 40957993, 2025). "Interestingly, in the COAD, DLBC, PAAD, READ, and STAD datasets, both IL7 and BCL10 were expressed higher in the cancer group than in the normal group." (PMID 38289597, 2024). "Multiple cancer types in TCGA shared common ISGS genes (CX3CR1, IL7, and HLA-B)." (PMID 39796714, 2024). "Several preclinical studies have demonstrated the efficacy of IL‐7 in various cancer types with or without combined therapeutic agents." (PMID 36583472, 2023).
cancer (continued). "Together, our data indicate that combining IL-7–CBD + CBD–IL-12 dual therapy with αPD-1 can overcome CPI resistance and deliver remarkable therapeutic outcomes in very challenging and clinically relevant cancer models." (PMID 38019919, 2023). "We still have a long way to go to understand the immune protective effects of IL-7 in various tumors and the optimal dose in clinical cancer patients without side effects." (PMID 36936961, 2023). "SDF-1 is an important niche factor in IL-7-expressing CAFs, indicating that the CXCL12 (SDF-1)/CXCR4 pathway may be a useful anti-cancer stem cell therapeutic (anti-CSC) target." (PMID 35735628, 2022). "Subsequently, increasing evidence proved that except for thymocytes and stromal non-hematopoietic cells, IL-7 is also secreted by lymphoid organs, non-lymphoid tissues, and even cancers." (PMID 36389666, 2022). "Clinical trials showed the benefit of IL-7 without severe adverse events and immune restoration in patients with cancer, septic shock and chronic viral infection including HIV." (PMID 34603318, 2021). "TIL-iPS-T were co-cultured with GFP-transduced cancer spheroids at a ratio of 1:1 in phenol red-free D-MEM supplemented with 10% fetal bovine serum, 2 mM l-glutamine, 100 U/ml penicillin, 100 ng/ml streptomycin, 100 U/ml IL-2, 5 ng/ml IL-7, and 5 ng/ml IL-15." (PMID 34099861, 2021). "Our anti-MUC1-CAR4 T cells showed potent anti-cancer effect comparable to that of other studies in different cancer models using second- and third-generation anti-MUC1-CAR T cells, and also inverted cytokine receptor (IL-4R/IL-7) CAR T cells." (PMID 33737613, 2021). "Circulating levels of IL-7 are increased in patients with solid tumors compared to healthy patients; they are also higher in cancer patients with bone metastases than patients without bone metastases." (PMID 32326073, 2020). "In the context of cancer, generating more memory CD8 T cells (for example, through IL-7 or IL-15 pathways) may improve the outcomes." (PMID 33613548, 2020). "We compared the expression of the 15 immune gene cancer tissues and adjacent tissues in the TCGA-BLCA cohort and found that the expression of the CCR9, IL7, PTGER4, IL10, CTSG, and ZBTB16 proteins in the adjacent tissues was significantly higher than that in the cancerous tissues (P < 0.05)." (PMID 32655621, 2020). "IL-7 has been shown to promote immune reconstitution both from thymus-independent homeostatic expansion of peripheral T cells and thymopoiesis in different clinical settings including idiopathic CD4 lymphopenia, septic shock, and cancer." (PMID 32903778, 2020). "Previous studies reported that RNA m6A methylation could affect various biological processes and signaling pathways, such as self-renewal and tumorigenesis of cancer stem cells, RNA metabolism, the FTO/m6A/MYC/CEBPA signaling, and the IL-7/STAT5/SOCS pathways." (PMID 32419773, 2020). "IL-7 as an immunotherapeutic for cancer is particularly appealing since this cytokine does not induce hyperinflammation." (PMID 31185636, 2019). "In fact, research on IL-7 focused on its function as a “critical enhancer of protective immunity”, and its potential contribution to cancer development had not entered the scene until recently." (PMID 31185636, 2019). "In our group, systemic IL-7 in GC was the lowest in the examined cancers and did not significantly differ as compared to the controls." (PMID 31185636, 2019). "IL-7 overexpression was more pronounced in Stage 3/4 and N1 cancers as a result of decreased cytokine expression in noncancerous tissue." (PMID 31185636, 2019). "Unlike the other γ-chain cytokines tested as therapeutics (e.g. IL-2), application of IL-7 in cancer immunotherapy is particularly appealing, because it does not induce hyperinflammation." (PMID 27866242, 2017).
cancer (continued). "Analysis of ROC curves indicates that IL-7 (p = 0.0039), but not IL-6 (p = 0.2938) or IL-15 (p = 0.1804) titres were able to distinguish sera from patients with malignancy from those from patients with benign disease." (PMID 21943235, 2011). "Given that IL-7 is being studied in HIV and cancer treatments, measuring sCD127 may be important when assessing the outcomes of these therapies." (PMID 19690616, 2009). "We evaluated patients' bone homeostasis; we made peripheral blood mononuclear cell (PBMC) cultures to detect in vitro osteoclastogenesis; we dosed serum expression of molecules involved in cancer induced osteoclatogenesis, such as RANKL, OPG, TNF-alpha, DKK-1 and IL-7." (PMID 18978943, 2008). "Our results showed that monocytes alone were not able to support significant OC formation in either the presence or absence of IL-7, in both cancer patients and healthy controls (data not shown)." (PMID 17205128, 2006). "Serum IL-7 levels were highest in osteolytic cancer patients, followed by cancer patients without bone lesions, and then healthy controls." (PMID 17205128, 2006). "These pathways are activated by both cancer cells and inflammatory stromal components, emphasizing the necessity for a comprehensive understanding of the interplay between angiogenic (VEGF, HGF) and immunoregulatory (IL-7, LIF) signals to fully comprehend the mechanisms of immune escape." (PMID 41597220, 2026). "However, to date, no comprehensive review has compiled evidence related to IL-7 expression in the context of cancer immunovirotherapy." (PMID 40957993, 2025). "Similarly, the viral expression of IL-7 alone does not consistently eradicate cancers or achieve durable efficacy." (PMID 40957993, 2025). "Additionally, IL7R signaling, important for the survival and proliferation of naive and memory T cells as previously discussed, was also reduced in Arms B and C as compared to Arm A. Within our data, IL7, a ligand for IL7R, was detected in Tregs and cancer cells." (PMID 39811671, 2025). "In summary, these results obtained in a spontaneous large animal cancer model indicate that addition of OX40/TLR immunotherapy to SBRT exerts important immunological effects both locally (Treg, macrophage, and T cell depletion) and systemically (increased circulating IL-7 concentrations)." (PMID 35055015, 2022). "Thus, we are going to construct the fourth-generation CAR-T cells to secrete a PD-1- or/and CTLA-4-blocking scFv together with IL-7 and CCL19, which may maximize the efficiency of CAR-T therapy for malignant solid tumors." (PMID 36479116, 2022). "Although recombinant IL-7 immunotherapy has had some success in clinical trials for treating septic shock, infection, and cancer remission, along with some early promise in the setting of HCT, further studies are necessary to identify a strategy for thymus-dependent IL-7 therapy." (PMID 32903477, 2020). "Besides, the effects of IL-7 for NKG2D CAR T cell functions were evaluated in the absence of Tregs, MDSCs, M2-macrophages and immune checkpoint molecules which created an immune-suppressive environment in cancer tissues." (PMID 32698361, 2020). "This may result from most of the patients enrolled for serum analysis of IL-7 having advanced cancers, not amenable for curative resection." (PMID 31185636, 2019). "Moreover, we showed the capability of IL-7 to stimulate spontaneous osteoclastogenesis of bone metastatic patients and to induce osteoclastogenesis in cancer patients without bone involvement." (PMID 17205128, 2006). "Taken together, these models consistently show that the elevated IL‐7 methylation observed in ICU patients is not explained by age, mortality, or malignancy." (PMID 41523740, 2026). "This has been confirmed in conditions including cancer and HIV infection, but not in RA where lymphodepletion did not lead to IL-7 accumulation." (PMID 25533722, 2014).
cancer (continued). "These cytokines were recently described to recruit and activate CD56+ cells for an innate immune response and were secreted independently of engineering IL7/IL12 secretion and may activate non-specific cytotoxicity against cancer cells that is further boosted by IL12 of engineered MSC." (PMID 32260097, 2020).
infection (181 papers, 2004 to 2026). The state of being infected such as from the introduction of a foreign agent such as serum, vaccine, antigenic substance or organism. "Minimally overlapping biomarker distributions were observed between EcoHIV-infected and sham mice, with distribution along the PC2 axis corresponding with EcoHIV infection status (EcoHIV was associated with High IL-13, sham was associated with High IL-7)." (PMID 38786105, 2024). "IL-7 causes upregulation of multiple adhesion molecules on lymphocytes that help traffic lymphocytes from the circulation to sites of inflammation or infection." (PMID 36906875, 2023). "Relative changes in IL-7 at 72 h compared to baseline (ΔIL-772h/0) was significantly associated with both surgical approaches (P = 0.019) and occurrence of infections (P = 0.042)." (PMID 29904108, 2018). "In the present study, we administered fully glycosylated simian IL-7 to rhesus macaques during the acute phase of infection with a pathogenic SIV strain (mac251)." (PMID 22511868, 2012). "In contrast, infection with the L1 lineage was associated with greater increase of cytokines with Th1/Th17–like activity (IL-12 and IL-17) and IL-7, a cytokine that promotes lymphocyte development in the thymus and maintains survival of naive and memory T cell homeostasis in the periphery." (PMID 29813061, 2018). "Low preoperative interleukin-7 was associated with developing surgical site infection." (PMID 29904108, 2018). "In the present study, recombinant, fully glycosylated simian IL-7 (50 μg/kg, s.c., once weekly for 7 weeks) was administered to 6 rhesus macaques throughout the acute phase of infection with a pathogenic SIV strain (mac251); 6 animals were infected at the same time and served as untreated controls." (PMID 22511868, 2012). "Additionally, intravenous administration of lentivirus causes infection of tissues known to be enriched in human immune cells, including the spleen and bone marrow, or which function as an endogenous source of IL-7, such as the liver." (PMID 20700454, 2010). "Notably, proinflammatory cytokine genes Il-1α, Il-6, Il-7, and Il-17, as well as anti-inflammatory genes Il-6 and Il-13, were downregulated after an infection caused by the 267/47 strain compared to those after infection with the H37Rv strain." (PMID 34442871, 2021). "The higher expression of MIP-1β, IL-8, MCP-1, GM-CSF, and IL-7 in this group suggests a more robust and effective immune response during the early stages of infection, potentially contributing to improved clinical outcomes." (PMID 40356822, 2025). "Including lymphoid lineage by cytokines presumably IL-7 and IL-15 with longer-term incubation would recapitulate the infection and downstream inflammatory events more precisely." (PMID 38627497, 2024). "The effect of IL-7 to induce lymphocytes to leave the bloodstream and migrate to sites of infection is most readily observed by the rapid fall in the ALC that occurs within hours after IL-7 administration." (PMID 36906875, 2023). "High concentrations of IFNɣ, TNFα, IL-10, IL-13, and MIP-1β were found during infection, as well as high concentrations of IL-7 and MCP-1 after recovery, in both the hospital ward and the ICU." (PMID 36975498, 2023). "Plasma levels of IL-4, IL-7, and IL-15 were similar at acute infection and 3 months but declined at later time points, suggesting a slow recovery of T-cell-related perturbations within 12 months." (PMID 37310006, 2023). "Significantly increased levels of IL-7 were observed in both groups six months after the infection (visit 3), particularly in patients admitted to the ward (p = 0.026)." (PMID 36975498, 2023). "The cytokine IL-7, which also plays a role in the recruitment and migration of innate immune cells, reached its peak by D2 post-infection (p<0.05 vs control), before its concentration plateaued." (PMID 37649477, 2023).
infection (continued). "Further studies are required to define the relationship between IL-7 and PD-1 in an acute infection setting and the mechanism by which this specifically affects T cells in an antigen-specific manner." (PMID 34997007, 2022). "The release of pro-inflammatory (Th1) cytokines in response to infection promotes cell survival and a hypermutable state, whereas the release of Th2 cytokines and interleukin-7 (IL-7) stimulates immature B-cell proliferation, including preleukemic cells." (PMID 35201533, 2022). "For adult CAP with risk of severity we propose a pathogenic model characterized by a pattern of a high level of sIL7R and a diminished IL-7 concentration, which tend to decrease T lymphocyte activity and therefore, the control of the infection." (PMID 35907923, 2022). "In an infection model of Citrobacter rodentium, intestinal mucosa-derived IL-7 protected the host by controlling bacterial burden and intestinal damage." (PMID 35280991, 2022). "It is conceivable that IL-7 mediates a B-T cell interaction that maintains control of infection in subclinical cows." (PMID 36477266, 2022). "When is the most suitable time to apply IL-7 to enhance immune reconstitution after infection with a specific pathogen?" (PMID 34925323, 2021). "Expression analyses of the published data set GSE14931227 shows that the infection of human intestinal organoids with SARS-CoV-2 can indeed induce the expression of Il7." (PMID 34045640, 2021). "On day 6 post-infection, the PBMCs were synchronized at G0 via serum starvation for three days, while cART/IL-7 treatment continued." (PMID 33916140, 2021). "A Receiver Operator Characteristics analysis showed that the levels of just two cytokines, ITAC and IL-7, were highly predictive of future infection." (PMID 33731158, 2021). "The PLS analysis showed that levels of ITAC, IL-5, IL-7, IL-8, and MIP-1α were associated with pre-infection." (PMID 33731158, 2021). "While elevated levels of Fractalkine, ITAC, IL-7, IL-8, and TNFα are observed for both countries in their respective pre-infection groups, they differ in that they exhibit additional biomarkers unique to each country." (PMID 33731158, 2021). "If an IL-7 value above 6.99 pg/ml was added to the model, the probability of identifying pre-infection individuals increased to 0.97." (PMID 33731158, 2021). "In our analysis, after infection diagnosis in susceptible dogs, PGE2 correlated with TNFα, IL-2, IL-15, and IL-7, most of them with pro-inflammatory functions, possibly attempting to decrease the inflammatory immune response." (PMID 33617528, 2021). "In Zambia, Fractalkine, ITAC, IL-7, IL-8, IL-23, and TNFα concentrations were significantly increased in the pre-infection group compared to the uninfected group in univariate comparisons." (PMID 33731158, 2021). "The gene encoding T-cell homeostatic cytokine IL-7 (IL7) was induced in cDC1, cDC2, and monocytic cells after infection with Eystrup, but only in cDC2 with PdR." (PMID 32733474, 2020). "Protection from infection was increased from ~80% in the chIL-2 or chIL-7 vector alone groups to 93% seen in the IL-2/IL-7 bicistronic vector group." (PMID 31137731, 2019). "Dam 2 had an increase in IL-1β, IL-2, IL-6, IL-7, IL-12, IL-15, IL-16 and IL-17A, peaking on day 14 post-infection for all but IL-12 and IL-15 which peaked on day 7 post-infection." (PMID 30657788, 2019). "Depletion results from both direct infection and bystander loss of memory CD4+ T cells in part attributed to dysregulated IL-7/IL-7R signaling." (PMID 31507594, 2019). "Infection of Haemophilus influenzae (NTHi) results in IL-12 and IL-7 synergistically controlling granzyme B by upregulating the IL-12 receptor in lung CD4+ and CD8+ T cells, which are used for increasing antibacterial response." (PMID 31915416, 2019). "It is therefore possible that the effect of IL-7 in resting T cell infection relates to this inhibition of FOXO1, but this requires further exploration." (PMID 31042779, 2019).